MEN1 (menin 1)
Diseases named in the same sentence as MEN1 in open-access papers (continued):
Sharing a sentence is not in itself a finding about the gene and the disease.
neuroendocrine tumors (continued). "We aimed to provide an in-depth analysis with respect to three turning points in pancreas involvement in primary hyperparathyroidism (PHP): hypercalcemia-induced pancreatitis (HCa-P), MEN1 (multiple endocrine neoplasia)-related neuroendocrine tumors (NETs), and insulin resistance (IR)." (PMID 38928056, 2024). "MEN1, DAX, and ATRX mutations are associated with well-differentiated neuroendocrine tumors (NETs)." (PMID 37373998, 2023). "The clinical criterion for the diagnosis of MEN1 is the presence of two of the three major neuroendocrine tumor (NET) types in an index patient, i.e., tumors of the parathyroid, pituitary, and/or pancreatic islet cells, or a MEN1-associated tumor in a family member of a patient with MEN1." (PMID 35287658, 2022). "pNETs are known to have elevated GLI1 levels in the absence of menin, implying that inhibition of GLI1 could suppress formation of MEN1-related neuroendocrine tumors." (PMID 35747820, 2022). "MEN1 is difficult to be distinguished from normal neuroendocrine tumors." (PMID 32126984, 2020). "The clinical presentation of MEN1 usually manifests as occurrence of tumors in the parathyroid gland, anterior pituitary gland, and pancreatic islet cells, with less common occurrences that include adenomas of the adrenal glands and neuroendocrine tumors." (PMID 31727021, 2019). "There is increasing debate if such patients are correctly diagnosed as having MEN1 since some of these patients might have a sporadic coincidence of two neuroendocrine tumors." (PMID 30254610, 2018). "However, other gastroenteropancreatic neuroendocrine tumors, adrenocortical adenomas, or thyroid nodules can occur in MEN1." (PMID 26161274, 2015). "Therefore, tumor size is an important prognostic factor for MEN1 NF-neuroendocrine tumors, influencing progression and patient survival." (PMID 24213321, 2012). "The management of MEN1-neuroendocrine tumors is still controversial." (PMID 24213321, 2012). "Both the histological type and the size of MEN1 neuroendocrine tumors correlate with malignancy." (PMID 24213321, 2012). "Surgery is often the treatment of choice for MEN1-neuroendocrine tumors." (PMID 24213321, 2012). "Both the histotype of MEN1 neuroendocrine tumor and the size correlate with malignancy." (PMID 24213321, 2012). "The underexpression of these apoptosis-related genes may be related to neoplastic development or progression in these MEN1-related neuroendocrine tumors." (PMID 15691381, 2005). "Eight neuroendocrine tumors from six MEN1 patients were included in this study." (PMID 15691381, 2005). "However, not all patients analyzed in our study had developed PHPT at the time of blood sampling, making us speculate that the increased circulating miR-24-3p may have been due to a still undiagnosed PHPT or to the presence of other MEN1 neuroendocrine tumors." (PMID 40507887, 2025). "Current international MEN1 guidelines recommend annual biomarker screening of patients with MEN1, including chromogranin A (CgA) and pancreatic polypeptide (PP) screenings for diagnosis and follow-up of patients with gastroenteropancreatic neuroendocrine neoplasms (NENs)." (PMID 40455177, 2025). "Interestingly, PSIP1 has also been found to be mutated in a subset of neuroendocrine tumors (5%) lacking MEN1 gene alterations." (PMID 33641055, 2021). "Therefore, the authors conclude that allelic deletion of the MEN1 gene might reflect a pivotal event in the development of neuroendocrine tumors of patients with MEN1." (PMID 32126984, 2020). "In four MEN1 patients with persistent primary hyperparathyroidism after PTX, first-generation somatostatin analogs (SSA1) were prescribed for other neuroendocrine tumors." (PMID 39682626, 2024).
neuroendocrine tumors (continued). "The guidelines (GLs) by the Japanese Neuroendocrine Tumor Society (JNETS) recommend surgical resection for functioning duodenopancreatic neuroendocrine tumors (NETs), including gastrinomas, in patients with MEN1 (Grade A, 100% agreement among members)." (PMID 36473964, 2023). "Neuroendocrine tumors occur in ≈20% of MEN4 subjects, a significantly lower percentage than MEN1 (≈50%)." (PMID 35355569, 2022). "MEN1 and CDKN1B testing is recommended in patients with personal or family history of kidney stones, neuroendocrine tumours or pituitary tumours." (PMID 33805450, 2021). "Anlauf and his co-authors found that 13/28 (46.4%) duodenal gastrin-producing neuroendocrine tumors and 2/5 (40%) somatostatin-secreting neuroendocrine tumors revealed LOH of 11q13 from six patients with Zollinger–Ellison syndrome and MEN1." (PMID 32126984, 2020). "However, ultrasonography (US), Computed Tomography (CT), and/or Magnetic Resonance Imaging (MRI) cannot always provide satisfactory results in diagnosing neuroendocrine tumors, and furthermore, the diagnostic path for these lesions in MEN1 is not clear in literature." (PMID 24213321, 2012). "He had no family history of neuroendocrine tumors, gastrointestinal cancers, or inherited syndromes (e.g., MEN1, NF1)." (PMID 40869648, 2025). "Furthermore, we observe distinct drivers which are enriched in somatic aberrations in pancreatic (MEN1, ATRX, DAXX, DMD and CREBBP) and midgut-derived neuroendocrine tumors (CDKN1B)." (PMID 34326338, 2021). "- In a patient with a pHPT and PIT phenotype and no MEN1 mutation, other syndromes like FIPA and MEN4 should be considered as well as a sporadic co-occurrence of two neuroendocrine tumors." (PMID 30254610, 2018). "As opposed to their sporadic counterparts, MEN1-neuroendocrine tumors are characterized by early onset, multiplicity of lesions, variable expression of the tumors, and frequent propensity for malignant degeneration." (PMID 24213321, 2012). "Patients without family history of neuroendocrine tumors or other MEN1 manifestations and “only” uniglandular parathyroid disease might safely be discharged from further intensive follow-up." (PMID 30254610, 2018). "Therefore, we provide further evidence that parathyroid tumors in MEN1 are multiple monoclonal tumors and not hyperplastic changes, supporting the nomenclature of multi-glandular adenomas as suggested in the novel WHO classification of “Endocrine and Neuroendocrine Tumours” (5th edition, 2022)." (PMID 38244045, 2024).
gastrinomas (81 papers, 2005 to 2026). "Although the majority of gastrinomas occur sporadically, a substantial proportion is linked to multiple endocrine neoplasia type 1 (MEN1)." (PMID 41406116, 2025). "Similar to our review, it has previously been reported that approximately 80 percent of gastrinomas are sporadic, and that 20 to 30 percent occur in association with MEN1." (PMID 40941664, 2025). "When a gastrinoma is associated with MEN1, there is extremely rarely a single lesion; generally, there are multiple pancreatic or gastrointestinal locations." (PMID 39941198, 2025). "We report a rare combination of a middle-aged female with pancreatic VIPoma and MEN1 instead of gastrinoma, which is by far a more common association with MEN1." (PMID 39290926, 2024). "In gastrinoma, a high rate (about 40%) of somatic MEN1 mutations and deletions in chromosome 1q are reported." (PMID 36830839, 2023). "Duodenal micro-gastrinomas are the primary cause of ZES in most patients with MEN1, highlighting the importance of pancreaticoduodenectomy in treating ZES." (PMID 37867522, 2023). "Consistent with its ability to repress gastrin gene expression, a heterozygous MEN1 variant and two heterozygous mutations were identified in all patients diagnosed with duodenal and pancreatic gastrinomas in our previously published cohort." (PMID 37492626, 2023). "A case report describing that the removal of all gastrinomas in a patient with MEN1 caused the gastric NETs to disappear showed that gastrin is the dominating cause of these tumors also in this condition." (PMID 37686307, 2023). "In patients with gastrinomas located in the pancreas (approximately 25% of patients) and MEN1, the role of surgery remains debated, and a risk-benefit assessment should always be evaluated." (PMID 37103745, 2023). "A second study from the NIH was published in 2004 and included a systematic dermatologic examination in 110 consecutive patients with sporadic and MEN1-associated gastrinomas." (PMID 36325452, 2022). "In these transgenic mouse studies, neural crest-derived EGCs were implicated as potential cellular precursors to MEN1-related gastrinomas, thus shifting the current paradigm on the cellular origin of these cancers." (PMID 35330921, 2022). "Gastrinomas present either sporadically or associated with multiple endocrine neoplasms type 1 (MEN1), due to an autosomal dominant mutation in the MEN1 gene on chromosome 11q13." (PMID 32345299, 2020). "MEN1-associated gastrinomas exhibit a malignant course and metastasize to local lymph nodes and liver in about 50% of cases, even before diagnosis." (PMID 33312161, 2020). "More than 80% of MEN1-associated gastrinomas exhibit, at pathology, multiple microgastrinomas within the first and second duodenum portion." (PMID 33312161, 2020). "There is no clear association with known genetic syndromes, but familial cases have been observed and about one third of cases present as multicentric tumors, similarly to MEN1-associated gastrinomas." (PMID 30657883, 2019). "In particular, gastrin-expressing duodenal NETs are often associated with MEN1 and show a global methylation profile similar to pancreatic gastrinomas." (PMID 30657883, 2019). "Treatment of MEN1-associated gastrinomas is primarily comprised of medical therapy which aims to decrease gastric acid secretion through the use of histamine 2-receptor antagonists, proton pump inhibitors, and/or somatostatin analogs (SSAs)." (PMID 31263451, 2019). "Lymph node metastases do not inevitably result in a poor prognosis or a high probability that clinically significant metastases will occur, and the risk of death from lymph node metastases due to MEN1 associated gastrinoma is less than that for sporadic cases." (PMID 31263451, 2019). "The prognosis of patients with MEN1-associated gastrinomas is associated with tumor size and the presence of hepatic metastases, with increased risk of hepatic metastases with increasing tumor size." (PMID 31263451, 2019).
gastrinomas (continued). "Typically, patients with MEN1 associated gastrinoma present at a younger age than in sporadic cases." (PMID 28965289, 2017). "There was a possibility that the skin lesions were associated with the MEN1 and that the gastrinoma occurred in the context of MEN1." (PMID 16042772, 2005). "The vast majority of MEN1-associated gastrinomas are located in the duodenum." (PMID 38893191, 2024). "Surgery may be considered in MEN1-associated metastatic gastrinomas confined to the liver if at least 90% of the identifiable tumor burden can safely be removed." (PMID 38893191, 2024). "Results from the DMSG showed that MEN1-related gastrinomas are associated with decreased life expectancy, and FSG levels ≥ 20× upper limit of normal, size of PanNETs ≥ 2 cm, and the presence of liver metastases are independent prognostic factors of overall survival (OS)." (PMID 38893191, 2024). "MEN1-associated neoplasms generally display a more aggressive clinical phenotype (e.g., multifocal tumors), yet surveillance in this population remains insufficient as upward of 60% of MEN1-gastrinoma cases present with metastases upon diagnosis." (PMID 37492626, 2023). "With background of Zollinger-Ellison Syndrome and MEN1 with heterozygous mutation with gastrinoma of the duodenum, and frailty he was advised to continue with Proton Pump Inhibitors with twice weekly correction of Magnesium infusions, and Iron tablets following Multi-disciplinary meeting." (PMID 34290814, 2021). "Most gastrinomas are sporadic (75%–80%), and approximately 20–25% are associated with MEN1." (PMID 33204258, 2020). "Usually, MEN1 gastrinomas are small (less than 0.5 mm) and multiple, with a frequent rate of malignant progression and metastases development, being, together with severe ulcers, one of the most common causes of MEN1-related premature deaths." (PMID 30428914, 2018). "Long-term unrecognised and untreated gastrinomas and MEN1-related malignancies were the most common causes of death among our patients, confirming data from a GTE study which indicated duodenopancreatic and thymic NETs as responsible for increased risk of death in MEN1 patients." (PMID 30428914, 2018). "Although MEN1 is frequently associated with gastrinomas, these are usually duodenal in origin." (PMID 28965289, 2017). "In addition, most MEN1-associated gastrinomas are located in the duodenum." (PMID 38893191, 2024). "However, nonsense mutations (Tyr312Stop and Arg460Stop) have been detected in MEN1 families with the Burin or prolactinoma variant which is characterized by a high occurrence of prolactinomas and a low occurrence of gastrinomas." (PMID 23933118, 2014). "SST‐PET/CT has a superior sensitivity for the detection of PanNETs and gastrinomas as well as locoregional and distant metastases in patients with MEN1 compared with conventional imaging." (PMID 39587981, 2025). "The presence of MEN1 in ZES patients has important effects on the pathology of the gastrinoma and its behavior, the prognosis of the patient, and all aspects of the management of the patient, including the need for genetic counseling." (PMID 41463062, 2025). "For gastrinomas, usually small, multiple and duodenal in MEN1, conventional imaging has very low sensitivity, and biochemical screening is the cornerstone." (PMID 39587981, 2025). "With ZES/MEN1 for assessment of the gastrinoma, almost all guidelines recommend an initial conventional cross-sectional imaging study (CT, MRI) when the ZES diagnosis is established." (PMID 41463062, 2025). "In the study of patients with sporadic ZES, 25% had gastrinomas which demonstrated aggressive growth behavior during the study period, differing from patients with MEN1/ZES, with only 14% demonstrating aggressive growth during the study period." (PMID 41463062, 2025). "Type-2 G-NETs are the least common subtype (5-10%) and usually occur in response to gastrinomas (gastrin-producing tumors), also termed Zollinger Ellison Syndrome (ZES), associated with MEN1." (PMID 39669826, 2024).
gastrinomas (continued). "These tumors tend to emerge early in MEN1, even earlier than gastrinomas, with the youngest documented case found in a 5-year-old girl." (PMID 39201946, 2024). "The 5- and 10-year OS rates for patients with MEN1-related gastrinoma were 83% and 65%, respectively, significantly lower compared to MEN1 patients without gastrinoma." (PMID 38893191, 2024). "In MEN1 patients, where multiple small duodenal gastrinomas are common, treatment becomes more complicated." (PMID 39201946, 2024). "Early diagnosis is a prognostic factor in MEN1 patients and biochemical identification of hypergastrinemia has been shown to recognize the presence of gastrinomas before they are seen on endoscopy." (PMID 39669826, 2024). "Gastrinomas are rare in children with MEN1, but when present, they can be aggressive and present with lymph node and liver metastases in 34–85% and 6–16% of cases, respectively, at the time of diagnosis." (PMID 38893191, 2024). "We reviewed these articles, and found that in one, the authors described successful curative resection with PD for gastrinomas in MEN1 patients." (PMID 36473964, 2023). "Given that LOH at MEN1 loci occurs in less than 50% of MEN1-gastrinomas, we investigated the possibility that alternative posttranslational mechanisms regulate menin protein expression in the context of incomplete LOH." (PMID 37492626, 2023). "In this review, we discuss the serious side effects and tumorigenic effects of the prolonged use of PPIs and the safety and curability of surgery, supported by our results of curative surgery for gastrinomas in 20 patients with MEN1 over 30 years." (PMID 36473964, 2023). "In the presence of hypergastrinism, the preferred type of surgery was PD, since the great majority of MEN1 gastrinomas are located in the duodenal wall." (PMID 37894286, 2023). "In our series of PPTD for 10 patients with MEN1 and gastrinomas, the mortality rate was 0% and the morbidity rate was less than 10%." (PMID 36473964, 2023). "Instead, in MEN1-related patients with gastrinoma, 5- and 10-year overall survival rates were 83% and 65%, respectively." (PMID 36830839, 2023). "Considering these facts, we think that surgical treatment should be the initial treatment recommendation for gastrinomas in MEN1 patients, instead of long-term PPIs." (PMID 36473964, 2023). "We believe that MEN1 patients with gastrinomas should be treated with PPIs in the short term to be better prepared for resection surgery." (PMID 36473964, 2023). "In patients with gastrinoma and MEN1, the prognosis seems to be better compared to patients with sporadic tumors particularly for those patients with lesions less than 2.5 cm." (PMID 37103745, 2023). "Since the development of the SASI test, the number of gastrinomas from patients with MEN1 that have been resected and pathologically examined has increased." (PMID 36473964, 2023). "We also report our results of performing curative surgery for gastrinomas in 20 patients with MEN1 over 30 years." (PMID 36473964, 2023). "A recent study showed that MEN1-related gastrinoma has some different clinical features than sporadic gastrinoma, such as tumor size and overall survival." (PMID 38087239, 2023). "We also performed PD which clearly proved that gastrinomas in MEN1 patients are predominantly located in the duodenum." (PMID 36473964, 2023). "There was definite evidence of gastrinoma or PA only as of the first manifestation of MEN1 in one (1.8%) and three (5.5%) patient, respectively." (PMID 35698198, 2022). "Here, we show a case of a 52-year-old man diagnosed with MEN1 through gastrinoma, parathyroid adenoma and gene detection." (PMID 36292242, 2022). "Approximately 25% of MEN1 patients die of a malignant gastrinoma (gastrointestinal neuroendocrine tumors) or foregut carcinoid tumor." (PMID 35255927, 2022). "Results: 35 patients (16 female, 19 male) with MEN1-ZES due to duodenopancreatic gastrinomas with a median age of 42 (range 30–74) years were included." (PMID 35454834, 2022).